NUDT12 (nudix hydrolase 12)
Description:
mRNA decapping enzyme that specifically removes the nicotinamide adenine dinucleotide (NAD) cap from a subset of mRNAs by hydrolyzing the diphosphate linkage to produce nicotinamide mononucleotide (NMN) and 5' monophosphate mRNA. The NAD-cap is present at the 5'-end of some RNAs; in contrast to the canonical N7 methylguanosine (m7G) cap, the NAD cap promotes mRNA decay. Preferentially acts on NAD-capped transcripts in response to nutrient stress. Also acts on free nicotinamide adenine dinucleotide molecules: hydrolyzes NAD(H) into NMN(H) and AMP, and NADPH into NMNH and 2',5'-ADP. May act to regulate the concentration of peroxisomal nicotinamide nucleotide cofactors required for oxidative metabolism in this organelle. Regulates the levels of circadian clock components PER1, PER2, PER3 and CRY2 in the liver (By similarity).
Synonyms: DKFZP761I172
Tractability: Small molecule: a structure with a bound ligand is known. PROTAC: ubiquitination databases record sites on it; its protein half-life has been measured.
Gene: Protein-coding gene on chromosome 5 (103,548,855 to 103,562,806, reverse strand). Ensembl gene ENSG00000112874.
Subcellular location: Cytoplasm; Peroxisome; Cytoplasmic granule
Pathways (Reactome):
Metabolism: Nicotinate metabolism
Gene Ontology:
Molecular function: NAD+ diphosphatase activity; NADH pyrophosphatase activity; NADPH pyrophosphatase activity; phosphodiesterase decapping endonuclease activity; protein binding; RNA NAD-cap (NMN-forming) hydrolase activity; magnesium ion binding; zinc ion binding; catalytic activity, acting on RNA; hydrolase activity; metal ion binding; pyrophosphatase activity
Biological process: mRNA methylguanosine-cap decapping; NAD+ catabolic process; NAD-cap decapping; NADP+ catabolic process; circadian regulation of gene expression; mRNA catabolic process; nicotinate metabolic process; mRNA metabolic process
Cellular component: cytoplasm; nucleus; peroxisome; peroxisomal matrix
Genetic constraint (gnomAD): Loss-of-function variants: 28 observed, 30.98 expected, observed/expected ratio (o/e) 0.9, 90% interval 0.67 to 1.24. The upper end of that interval is the gene's LOEUF score, 1.24, which puts it in group 5 of 6, group 1 being the genes least tolerant of losing a copy. Missense variants: 471 observed, 449.46 expected, observed/expected ratio (o/e) 1.05, 90% interval 0.97 to 1.13. Synonymous variants: 168 observed, 153.09 expected, observed/expected ratio (o/e) 1.1, 90% interval 0.97 to 1.25.
Homologues: Orthologues: chimpanzee NUDT12 (99% identical), macaque NUDT12 (98% identical), rabbit NUDT12 (93% identical), pig NUDT12 (93% identical), dog NUDT12 (92% identical), guinea pig NUDT12 (90% identical), mouse Nudt12 (88% identical), rat Nudt12 (88% identical), tropical clawed frog nudt12 (65% identical), zebrafish nudt12 (51% identical), Caenorhabditis elegans ndx-9 (23% identical). Paralogues in human: NUDT17 (9% identical), NUDT1 (8% identical), NUDT18 (8% identical).
Diseases named in the same sentence as NUDT12 in open-access papers:
NUDT12 is named in the same sentence as 19 diseases in open-access papers, as found by Europe PMC text mining. Sharing a sentence is not in itself a finding about the gene and the disease. The quoted sentences say what the papers report.
breast cancer (2 papers, 2019 to 2025). A primary or metastatic malignant neoplasm involving the breast. "No direct association was observed between TRPC4AP and NUDT12 and mammary tumors." (PMID 40839607, 2025).
cyst (1 paper, 2025). A sac-like closed membranous structure that may be empty or contain fluid or amorphous material. "To explore potential roles of Subclade II NUDTs in plant‐pathogen interactions, we first examined transcript abundance of NUDT12, NUDT13, and NUDT16 during Arabidopsis infection by cyst nematodes (CN) using previously published transcriptomic data." (PMID 41165244, 2025).
diabetes (1 paper, 2024). "Our results not only validated the upregulated expression of NUDT12, but also revealed its involvement in insulin signaling and diabetes-related pathways through enrichment analysis." (PMID 38464965, 2024).
glioma (1 paper, 2024). A benign or malignant brain and spinal cord tumor that arises from glial cells (astrocytes, oligodendrocytes, ependymal cells). "NUDT12, which is involved in cellular energetics, serves as a critical prognostic biomarker in glioma progression." (PMID 38584840, 2024).
maturity onset diabetes (1 paper, 2024). "The results of GSEA suggested that the ENPP3 was enriched in Toll like receptor signaling pathway and natural killer cell mediated cytotoxicity, NUDT12 was enriched in maturity onset diabetes of the young and insulin signaling pathway." (PMID 38464965, 2024). "GSEA suggested that ENPP3 was enriched in Toll like receptor (TLR) pathway, NUDT12 was enriched in maturity onset diabetes of the young and insulin pathway." (PMID 38464965, 2024). "The results showed NUDT12 is enriched in maturity onset diabetes of the young (MODY), a common form of monogenic type 2 diabetes in youth." (PMID 38464965, 2024).
Neurotoxicity Syndromes (1 paper, 2024). "A total of 59 biomarker-associated diseases were obtained through the CTD database, and a total of 55 biomarker-disease association pairs were obtained, such as ENPP3 and Glucose Intolerance, and NUDT12 and Neurotoxicity Syndromes." (PMID 38464965, 2024).
thyroid autoimmunity (1 paper, 2019). "Genetic variants in the 500 kb window around this SNP and NUDT12 were already associated with depressive symptoms and depression, thus liking yet another closely related personality trait with thyroid autoimmunity." (PMID 30926877, 2019).
cancer (4 papers, 2020 to 2025). A tumor composed of atypical neoplastic, often pleomorphic cells that invade other tissues. "NUDT12, part of the Nudix family, impacts the regulation of the nucleotide pool, affecting DNA stability and repair in cancer." (PMID 40722386, 2025). "What’s more, the expression of some writer genes (METTL1 and WDR4) and reader genes (AGO2 and NCBP2) was significantly upregulated in most cancers, while the expression of some eraser genes (NUDT12 and NUDT16) and some reader genes (EIF4E3) were downregulated in most cancers." (PMID 36339001, 2022). "Compared to normal tissues, most genes were upregulated in cancer tissues, while EIF4E3, NUDT12, and NUDT4 were downregulated." (PMID 40018039, 2025).
infection (1 paper, 2025). The state of being infected such as from the introduction of a foreign agent such as serum, vaccine, antigenic substance or organism. "NUDT12 showed no significant expression changes at either stage of infection." (PMID 41165244, 2025).
NUDT12 also shares sentences with these, for which no sentence is quoted: psychiatric diseases (2 papers); depression (1); HIV-1 infection (1); insomnia (1); maturity-onset diabetes of the young (1); metastatic melanoma (1); nematode infection (1); neurological diseases (1); oral cancer (1); schizophrenia (1).